CLPSL1 (colipase like 1)
Synonyms: C6orf127; dJ510O8.6; ESP32
Tractability: Antibody: UniProt places it where antibodies can reach, with medium confidence; UniProt predicts a signal peptide or a membrane-spanning region; its Gene Ontology location is reachable by antibodies, with medium confidence.
Gene: Protein-coding gene on chromosome 6 (35,781,019 to 35,793,675, forward strand). Ensembl gene ENSG00000204140.
Subcellular location: Secreted
Gene Ontology:
Molecular function: enzyme activator activity
Biological process: digestion; lipid catabolic process
Cellular component: extracellular region
Genetic constraint (gnomAD): Loss-of-function variants: 9 observed, 7.24 expected, observed/expected ratio (o/e) 1.24, 90% interval 0.74 to 1.87. That is too few expected variants to judge how well the gene tolerates losing a copy. Missense variants: 149 observed, 127.33 expected, observed/expected ratio (o/e) 1.17, 90% interval 1.02 to 1.34. Synonymous variants: 49 observed, 46.67 expected, observed/expected ratio (o/e) 1.05, 90% interval 0.83 to 1.33.
Homologues: Orthologues: chimpanzee CLPSL1 (98% identical), macaque CLPSL1 (60% identical). Paralogues in human: CLPS (28% identical), CLPSL2 (17% identical), LRCOL1 (13% identical).
Diseases named in the same sentence as CLPSL1 in open-access papers:
CLPSL1 is named in the same sentence as 3 diseases in open-access papers, as found by Europe PMC text mining. Sharing a sentence is not in itself a finding about the gene and the disease. The quoted sentences say what the papers report.
breast carcinoma (2 papers, 2020 to 2025). "It has been reported that CLPSL1 is associated with a prognostic factor of breast cancer." (PMID 32467720, 2020). "Our database identified well-known fusion genes that are commonly associated with breast cancer, such as ESR1::CCDC170, and revealed previously unreported fusion genes, including TPTE2::MRPS31P2 and LHFPL5::CLPSL1." (PMID 41213951, 2025). "The most frequently occurring fusion genes in each subtype were TTC6::MIPOL1 in HR+/HER2‒ breast cancers, LHFPL5::CLPSL1 in triple-negative breast cancer (TNBC), and TPTE2::MRPS31P2 in HER2+ breast cancers." (PMID 41213951, 2025).
CLPSL1 also shares sentences with these, for which no sentence is quoted: pancreatic cancer (1 paper); triple-negative breast carcinoma (1).